CXCR4 (C-X-C motif chemokine receptor 4)
Diseases named in the same sentence as CXCR4 in open-access papers (continued):
Sharing a sentence is not in itself a finding about the gene and the disease.
rhabdomyosarcoma (14 papers, 2011 to 2025). A rare aggressive malignant mesenchymal neoplasm arising from skeletal muscle. "CXCR4 expression has been found to be associated with bone marrow metastases of breast and prostate cancer, and rhabdomyosarcoma." (PMID 24932293, 2014). "On one hand, it is known that CXCR4 expression is implicated in rhabdomyosarcoma progression, so we analyzed relapses and chemotherapy-resistant rhabdomyosarcoma tumors from pediatric patients and found that they had particularly high levels of CXCR4 expression." (PMID 31428099, 2019). "In a study investigating the CXCL12/CXCR4/ACKR3 axis in rhabdomyosarcomas, ACKR3 promoter activity was shown to depend on an NF-κB binding site." (PMID 35674847, 2022). "CXCR4 overexpression significantly enhanced cell motility, effect that was more robust in alveolar vs. embryonal rhabdomyosarcoma subtypes." (PMID 34440844, 2021). "We investigated the potential role of CXCR4 in chemotherapy resistance and relapse, by performing immunohistochemical analyses to evaluate CXCR4 expression in rhabdomyosarcoma tumor samples." (PMID 31428099, 2019). "In our cohort of pediatric rhabdomyosarcoma patients, we found a correlation between higher levels of CXCR4 expression at diagnosis and relapse." (PMID 31428099, 2019). "In this study, we propose a novel therapeutic approach based on anti-CXCR4 blocking antibody in combination with NKAE cell therapy to prevent rhabdomyosarcoma tumor implantation and lung metastasis." (PMID 31428099, 2019). "In rhabdomyosarcoma, shown to employ CXCR4-mediated mechanisms, ectopic expression of CXCR7 in rhabdomyosarcoma cells enhanced their metastatic potential in experimental metastasis revealed by intravenous tumor cell injection." (PMID 24040160, 2013). "Interestingly, previous studies in rhabdomyosarcoma cells demonstrated that CXCR4 overexpression was sustained by the upregulation of Sp transcription factors (80% of cases)." (PMID 34440844, 2021). "We analyzed CXCR4 expression in tumor samples from pediatric rhabdomyosarcoma patients." (PMID 31428099, 2019). "Interestingly, in a rhabdomyosarcoma xenograft model, a third murine anti CXCR4 mAb (clone CF172) showed some resistance to lymph node metastasis while had little effect on the primary tumor volume." (PMID 31428099, 2019). "In rhabdomyosarcoma, the CXCL12/CXCR4 axis is crucial for the metastatic process and high CXCR4 expression is associated with poor outcome." (PMID 34440844, 2021). "Accordingly, anti-CXCR4 blocking antibody (MDX1338) efficiently reduced migration and invasion of alveolar rhabdomyosarcoma RH30 cells." (PMID 34440844, 2021). "Consistent with these previous findings, our results for MDX1338, a fully human mAb blocking the CXCR4/CXCL12 axis, show that this mAb can efficiently decrease the migration and invasion indices of metastatic RH30 rhabdomyosarcoma cells in vitro." (PMID 31428099, 2019). "The results presented here demonstrate that combined treatment with the anti-CXCR4 mAb MDX1338 and NKAE cell therapy prevents rhabdomyosarcoma cells from migrating, invading, tumor implantation and the formation of lung metastases." (PMID 31428099, 2019). "Such enhanced tumor cell specific homing in the BM mediated by coexpression of both CXCR4 and CXCR7 receptors correlate with a previous study reported in a rhabdomyosarcoma model." (PMID 25955316, 2015). "Previous studies have shown that CXCR4 correlates with the expression of the angiogenic factor VEGF in STSs, and that the CXCR4/CXCL12 complex may participate in tumor dissemination and metastasis in rhabdomyosarcoma cell lines." (PMID 38893721, 2024). "Moreover, in assays in vitro, anti-CXCR4 blocking antibody (MDX1338) efficiently reduced migration and invasion of alveolar rhabdomyosarcoma RH30 cells." (PMID 31428099, 2019).
inflammatory bowel disease (13 papers, 2008 to 2026). A spectrum of small and large bowel inflammatory diseases of unknown etiology. "DNA microarray studies by Watanabe and co-workers demonstrated significant up-regulation of the CXCR6 motif in ulcerative colitis patients, whilst other work has indicated that the CXCL12/CXCR4 interaction is involved in several inflammatory conditions, including inflammatory bowel disease." (PMID 19555476, 2009).
type 1 diabetes (13 papers, 2012 to 2026). "Histological analysis of heart tissue showed that type I diabetes was associated with the development of extensive left ventricular perivascular fibrosis at 8 weeks and this was attenuated by both candesartan and the CXCR4 antagonist, AMD3465." (PMID 26214690, 2015). "Animals with type I diabetes (streptozotocin treated mice) or type II diabetes (Israeli Sand-rats) and controls were randomized to treatment with a CXCR4 antagonist, candesartan or vehicle control." (PMID 26214690, 2015). "A previous report showed that the expression of SDF-1α and CXCR4 is up-regulated in the tunica media of the thoracic aortas in streptozotocin-induced type-1 diabetes." (PMID 23185548, 2012). "However, percentage of CD34+CD45dimVEGFR2+ expressing CXCR4 was significantly higher in in the type 1 diabetes group (p = 0.050)." (PMID 34267242, 2021). "The MIF/CD74 signaling pathway promotes macrophage-mediated inflammation in type 1 diabetes, and MIF controls the recruitment of inflammatory cells via chemokine receptors CXCR2 and CXCR4." (PMID 34445689, 2021). "We investigated the influence of type 1 diabetes on circulating HPC and EPC numbers, and the cell surface expression of CXCR4 and CXCR7 on these cells, at rest and in response to a submaximal exercise bout." (PMID 34267242, 2021). "Within the type 1 diabetes group, exercised-induced increases of the HPCs and EPCs was significantly greater in the cells that also expressed CXCR4 or CXCR7, with the progenitor cells negative for a chemokine receptor having between 64 and 101% less mobilization." (PMID 34267242, 2021).
chronic myeloid leukemia (12 papers, 2012 to 2025). "In comparison to K562 (chronic myelogenous leukemia), there was high level of CXCR4 expression in Ramos cell line." (PMID 26646452, 2016). "In chronic myeloid leukemia (CML), CXCL12 is secreted by MSCs, reducing caspase 3 activity in a CXCR4-dependent manner and attenuating cell death induced by imatinib." (PMID 33472580, 2021). "In chronic myeloid leukemia (CML), CXCR4 expression is down-regulated by the fusion protein BCR-ABL, and associated with a defective adhesion of CML cells to bone marrow stroma." (PMID 32075106, 2020). "This has been elegantly demonstrated in chronic myeloid leukemia (CML) cells exposed to imatinib in the presence or absence of MSCs, leading to the proposition of combination therapy with imatinib and the CXCR4 antagonist AMD3100 to overcome MSC-mediated chemoresistance." (PMID 25474039, 2015).
head and neck cancer (12 papers, 2012 to 2024). A primary or metastatic malignant neoplasm affecting the head and neck. "The analysis of a single-cell sequencing dataset representing head and neck cancer clearly showed the expression variation between different cell types, with a significantly increased expression of CXCR4 in T cells and of FAP in fibroblasts, as expected." (PMID 36672341, 2023). "Furthermore, CXCL12-CXCR4 signaling is involved in stromal-immune crosstalk giving a rationale for the clinical investigation of CXCR4 inhibitors in combination with anti-PD1 in metastatic pancreatic (NCT04177810, NCT02826486) and head and neck cancers (NCT04058145)." (PMID 33066357, 2020). "Furthermore, we have also demonstrated that blocking CXCR4 with 1,1’ -[1,4-Phenylenebis(methylene)]bis-1,4,8,11-tetraazacyclotetradecane octahydrochloride (AMD3100), a CXCR4 antagonist, may be a potent anti-metastatic therapy for CXCR4-related head and neck cancer." (PMID 24236200, 2013).
pulmonary hypertension (12 papers, 2011 to 2025). Increased pressure within the pulmonary circulation due to lung or heart disorder. "CXCR4-positive cells have recently been implicated in the development of pulmonary arterial hypertension (PAH)." (PMID 32455728, 2020). "The chemokine receptor CXCR4 promoted hypoxia-induced pulmonary hypertension and vascular remodeling in rats, and inhibition of CXCR4 significantly attenuated these effects." (PMID 31191333, 2019). "Other studies have also reported that CXCR4 and/or c-Kit positive cells are critical in the development of pulmonary hypertension and vascular remodeling in rats." (PMID 31023308, 2019). "Inhibition of CXCR4 in chronically hypoxic mice prevents the accumulation of c-kit+ putative HPCs in pulmonary arteries and the development of pulmonary hypertension." (PMID 24587052, 2014). "We also found that specific inhibition of the CXCR4 in bone marrow cells attenuated hypoxia-induced pulmonary hypertension and vascular remodeling." (PMID 21294880, 2011). "In conclusion, this study found that CXCR4 plays an important role in development of hypoxia-induced pulmonary hypertension and vascular remodeling." (PMID 21294880, 2011). "We thereafter investigated the effect of the CXCR4 inhibitor on hypoxia-induced pulmonary hypertension in rats in this study." (PMID 21294880, 2011). "We also found that inhibition of the CXCR4 in bone marrow cells by shRNA electroporation also significantly attenuated hypoxia-induced pulmonary hypertension, right ventricular hypertrophy and vascular remodeling." (PMID 21294880, 2011). "In this study we found that a CXCR4 inhibitor significantly inhibited hypoxia-induced pulmonary hypertension, right ventricular hypertrophy and vascular remodeling of pulmonary arteries in rats." (PMID 21294880, 2011). "The results from our study further demonstrated the effect of CXCR4 in development of pulmonary hypertension and vascular remodeling in chronically hypoxic rats." (PMID 21294880, 2011). "In this study we investigated the role of CXCR4 in the development of pulmonary hypertension and vascular remodeling by using a CXCR4 inhibitor AMD3100 and by electroporation of CXCR4 shRNA into bone marrow cells and then transplantation of the bone marrow cells into rats." (PMID 21294880, 2011). "In addition, we electroporated CXCR4 shRNA into bone marrow cells and then transplanted the bone marrow cells with CXCR4 shRNA into rats to investigate the effect of CXCR4 on bone marrow cell migration in hypoxia-induced pulmonary hypertension." (PMID 21294880, 2011). "In this study, we observed that inhibition of the CXCR4 in bone marrow cells significantly decreased hypoxia-induced pulmonary hypertension and vascular remodeling, which indicated that bone marrow cell migration played a role in the development of pulmonary hypertension." (PMID 21294880, 2011). "Therefore, this is the first study to show that migration inhibition of bone marrow cells by CXCR4 shRNA inhibits development of hypoxia-induced pulmonary hypertension and vascular remodeling." (PMID 21294880, 2011). "Studies using mouse models of pulmonary hypertension suggest that targeting the TGF-β/CXCR7 and CXCR4 signaling pathways can alleviate pericyte dysfunction in PAH." (PMID 39450276, 2024). "CXCR4 plays a role in several diseases, including human immunodeficiency virus (HIV) infection, cancer, immunodeficiency, pulmonary artery hypertension (PAH), amyotrophic lateral sclerosis, and pulmonary injury." (PMID 32047668, 2020). "Accumulation of c-kit positive cells and SDF-1 and its chemokine receptor CXCR4 has been described in proximity of plexiform lesions while targeting of c-kit positive cells and CXCR-4 has been shown to ameliorate pulmonary hypertension in animal models." (PMID 30486375, 2018). "In this study we used a CXCR4 inhibitor, AMD3100, in rats to determine the role of CXCR4 in development of pulmonary hypertension and vascular remodeling." (PMID 21294880, 2011).
pulmonary hypertension (continued). "CXCR4 is the receptor for chemokine CXCL12 and reportedly plays an important role in systemic vascular repair and remodeling, but the role of CXCR4 in development of pulmonary hypertension and vascular remodeling has not been fully understood." (PMID 21294880, 2011). "However, the role of CXCR4 in pulmonary hypertension and remodeling has not been completely understood." (PMID 21294880, 2011).
astrocytoma (11 papers, 2008 to 2024). "We used primary human macrophages naturally expressing P2Y11, CXCR4 and CXCR7 on the one hand, and on the other, a P2Y11-recombinant astrocytoma cell line that naturally expresses CXCR7 but lacks CXCR4." (PMID 38472446, 2024). "In our side-by-side examinations, the astrocytoma cell line thus served as a natural CXCR4-knockout." (PMID 38472446, 2024). "Importantly, however, most astrocytoma cell lines lack CXCR4." (PMID 38472446, 2024). "In astrocytoma cells, the CCL20-enhancing effect of TC14012 can only be mediated by CXCR7, as these cells lack CXCR4." (PMID 38472446, 2024). "Absence of CXCR4 expression (astrocytoma) eliminated the need of PDE4 inhibition, altogether suggesting that CXCR4 serves as a checkpoint that regulates CXCR7 effects by keeping intracellular cyclic AMP levels low." (PMID 38472446, 2024). "The CXCL12/CXCR4 axis has gained increased focus during the recent decade and has been extensively studied in brain tumors (GBM, astrocytoma, medulloblastoma, oligodendroglioma, and oligodendroastrocytoma) due to its key role in the communication of tumor cells with their microenvironment." (PMID 35745762, 2022). "In astrocytoma, tumor progression may not be compatible with CXCR4 expression, since, according to our observations, CXCR4 would limit the pro-survival effect of CXCR7." (PMID 38472446, 2024). "Finally yet importantly, the absence of CXCR4 in astrocytoma cells eliminated the need for PDE4 inhibition." (PMID 38472446, 2024). "Using an astrocytoma cell line, naturally expressing CXCR7 but lacking CXCR4, P2Y11/IL-1R activation effectively induced and CXCR7 agonist TC14012 enhanced CCL20 production even in the absence of PDE4 inhibition." (PMID 38472446, 2024). "On the other hand, CXCR4 and CXCL12 expression frequently occurs in GBM proliferating vascular endothelium, but not in endothelial cells from astrocytomas in which proliferation of microvessels is less abundant." (PMID 24904289, 2014). "Consistent with the absence of CXCR4 and the resulting lack of requirement for PDE4 inhibition, a ten-fold lower concentration of IL-1ß was sufficient to induce high levels of CCL20 in the astrocytoma cells." (PMID 38472446, 2024). "In line with our hypothesis that CXCR4 has regulatory effects, P2Y11/IL-1R signaling was sufficient to induce CCL20 production in astrocytoma cells with no requirement for PDE4 inhibition." (PMID 38472446, 2024).
colorectal tumor (11 papers, 2008 to 2025). "Macrophage-specific deletion of CXCR4 or knockdown of HIF2A in colorectal tumor cells reduced M2 accumulation in peritumor tissue and subsequent local invasion of tumor cells." (PMID 40756343, 2025). "We next evaluated CXCR4 protein expression in tumor colonocytes from primary freshly isolated colorectal tumors and colonocytes from matched adjacent normal-appearing colonic mucosa." (PMID 32110952, 2020). "In summary, the present study showed that the expression of CXCL12 mRNA is higher in rectal tumours and CXCR4 mRNA was inversely correlated in colorectal tumours with a lymphatic invasion." (PMID 29887884, 2018). "Our study demonstrates that both the chemokine ligand CXCL12 and its receptor CXCR4 are expressed by colorectal tumour cells." (PMID 29887884, 2018). "In human specimens, the content of CD133+CXCR4+ cells was higher in liver metastases than in primary colorectal tumors." (PMID 22871210, 2012). "CXCR4 promoter methylation was detected in a minority of colorectal tumors in the TCGA." (PMID 32110952, 2020). "Colorectal tumour cells' differentiation induced the downregulation of CXCR4." (PMID 29887884, 2018). "However, other mechanisms are most likely responsible for tumor progression and dissemination, and the interaction between CXCL12 and its receptor CXCR4 was shown to play a major role in the settlement of colorectal tumor cells in the liver." (PMID 24629239, 2014). "We collected colorectal tumor specimens from 29 patients and determined the content of the CD133+CXCR4+ subpopulation using flow cytometry." (PMID 22871210, 2012).
gastric tumor (11 papers, 2014 to 2024). "Moreover, overexpression of CXCR4 in gastric tumor has been demonstrated to be associated with development of malignant ascites and peritoneal carcinomatosis." (PMID 24659999, 2014). "While, in most previous studies, the expression levels of CXCR4 were examined by immunohistochemical staining in primary gastric tumor tissues, the present study intended to investigate the expression profile of CXCR4 on the mRNA level." (PMID 35877436, 2022). "The expression levels of CXCR4 and NFE2L2 as well as four differentially expressed NRGs (SPP1, CXCL1, MMP9, and TIMP1) were validated in gastric tumor cells and clinical samples." (PMID 38221932, 2024). "In gastric tumor samples, elevated levels of DARPP-32, CXCR4, and CXCL-12 were noted compared to normal tissues, with statistical analysis confirming positive correlations between DARPP-32 and both CXCR4 and CXCL-12." (PMID 39767693, 2024).